RN7SL538P (RNA, 7SL, cytoplasmic 538, pseudogene)
Gene: Miscellaneous RNA gene on chromosome 1 (69,879,592 to 69,879,895, forward strand). Ensembl gene ENSG00000240692.
Homologues: Orthologues: chimpanzee Metazoa_SRP (99% identical), macaque Metazoa_SRP (85% identical). Paralogues in human: RN7SL2 (74% identical), RN7SL3 (74% identical), RN7SL1 (74% identical), RN7SL498P (72% identical), RN7SL5P (72% identical), RN7SL481P (71% identical), RN7SL4P (71% identical), RN7SL18P (71% identical), RN7SL230P (71% identical), RN7SL239P (71% identical), RN7SL296P (71% identical), RN7SL15P (70% identical), and 698 more.